IL18 (interleukin 18)
Diseases named in the same sentence as IL18 in open-access papers (continued):
Sharing a sentence is not in itself a finding about the gene and the disease.
Obesity (continued). "A hyperglycemic proinflammatory milieu that is consistently found in obesity/T2D can be expected to induce and promote the IL‐18R/IL‐18 expression in the adipose tissue which may have pathobiological implications in metabolic disease." (PMID 28508444, 2017). "GlycA was associated with increased IL-18 in those without RA but not in those with RA, again highlighting differences in inflammation associated with chronic inflammatory diseases and obesity." (PMID 27067270, 2016). "Given that IL-18 null mice exhibit hyperphagia, obesity and insulin resistance, the reduced levels of IL-18 may explain the observation that Nlrp3-/- mice fed a Western diet appeared to be more hyperphagic and tended to be heavier than WT mice." (PMID 27583382, 2016). "In summary our data show that lack of Il18 but not Il18r1 in mice led to an increased susceptibility to dietary obesity." (PMID 26656097, 2015). "Thus, recent data show that NLRP3-/- knockout mice do not increase weight when fed a high fat diet, and that elimination of NLRP3 expression prevents obesity-induced caspase-1 cleavage as well as IL1β and IL18 activation." (PMID 25020064, 2014). "Interestingly, increased IL-18 levels have also been detected in type-2 diabetes, obesity, and ischemic heart disease." (PMID 25147500, 2014). "Thus, further studies are needed to evaluate the role of IL-6 and IL-18 in the pathogenesis of obesity and insulin resistance." (PMID 24733068, 2014). "Since obesity has independent association with both OPN and IL-18, OPN and IL-18 showed a positive correlation with the fasting blood glucose which may be taken as a reasonable surrogate measure of the insulin resistance." (PMID 23675517, 2013). "Although a significant correlation of OPN and IL-18 with FBG, multiple regression analysis detected only significant independent association of IL-18 with FBG, indicating that the relationship of IL-18 with FBG is dependent on obesity." (PMID 23675517, 2013). "Elevated circulating interleukin 18 levels have been reported to be associated with metabolic syndrome independent of obesity and insulin resistance, however, in our present study; the myocardial gene expression of interleukin 18 was down-regulated." (PMID 23320804, 2013). "Indeed, several studies have shown elevated circulating IL-18 concentrations in subjects with obesity and insulin resistance." (PMID 22531046, 2012). "Our study suggests a strong positive association between circulating IL-18 levels and the MetS in apparently healthy Chinese, independent of obesity, fat mass index, adipokine and inflammation." (PMID 21437204, 2011). "In our study, PCOS patients complicated with IR and obesity presented with increased IL-18 level, and serum IL-18 concentration had positive correlation with IR and BMI, it seemed that IR and obesity may accelerate the increase of serum IL18 level." (PMID 21244650, 2011). "Since IL-18 is involved in the pathogenesis of different cardiovascular diseases, we conclude that IL-18 may represent a link between obesity and related co-morbidities in children and adolescents." (PMID 20169140, 2010). "Thus, future studies have to address the correlations between IL-18 levels, obesity, and infections in early life." (PMID 20169140, 2010). "The continuous decreased expression of Il18 in the proximal and middle part of the small intestine that we found after a high-fat diet intervention might suggest a role in dietary fat-induced obesity and insulin resistance." (PMID 18457598, 2008). "Consequently, the loss or gain of NLRP1 function recapitulates obesity-related phenotypes in mice lacking or overexpressing IL-18." (PMID 40243151, 2025). "Furthermore, IL-18 values showed a positive correlation with obesity, IR, and hyperandrogenism." (PMID 38540173, 2024). "However, the state of obesity might induce IL-18 resistance, which manifests as increased concentrations of this cytokine." (PMID 39275140, 2024).
Obesity (continued). "Inhibition of IL-18 may provide potential therapeutic effects for patients with obesity." (PMID 39275140, 2024). "IL-18 has increased expression in obesity and heart failure, contributes to heart rhythm disorders, and VT in mice, and our data established the novel finding that IL-18 may heighten cytokine effects on proarrhythmic ion channel functional phenotypes and VT risks." (PMID 39063055, 2024). "In the present cohort, obesity-linked variables, such as diabetes, dyslipidemia (low HDL cholesterol and high triglyceride levels) and elevations in systemic inflammatory markers (CRP, IL-6 and IL-18), were more common among individuals with complete fatty degeneration of thymus." (PMID 37653480, 2023). "However, also anti-obesity effects of IL-18 have been described." (PMID 37659013, 2023). "Therefore, we hypothesize that Vanin-2 may promote IL-18 secretion to maintain weight homeostasis and prevent excessive weight gain in individuals with obesity and insulin resistance." (PMID 38156278, 2023). "The tissue inflammatory state during obesity may be caused by TLR-4/NF-κB pathway activation in macrophages via FFA action, which promotes the synthesis and secretion of proinflammatory cytokines, including IL-6, TNF-α, IL-1β, and IL-18." (PMID 37372966, 2023). "Likewise, prior studies reported elevated IL-18 levels in individuals with obesity." (PMID 37659013, 2023). "Moreover, the postoperative serum IL-18 level of CRF rats fed with high-fat diet was significantly higher than that of CRF rats fed with conventional diet, which indicated that obesity caused by high-fat diet can further upregulate serum IL-18 levels in CRF rats." (PMID 34901204, 2021). "Moreover, plasma levels of mature IL-18, activated by the NLRP3 inflammasome, and TNF, a cytokine that could be activated down-stream to NLRP3 activation, were increased with obesity and markedly reduced in inflammasome deficient mice." (PMID 31379826, 2019). "However, somewhat paradoxically, IL-18 has anti-obesity effects." (PMID 30619282, 2018). "Altered expression of immune system molecules such as interleukins IL-1, IL-6, IL-18, tumor necrosis factor alpha (TNF-α), serum amyloid A (SAA), and plasminogen activator inhibitor-1 (PAI-1), among others, has been associated with the development of chronic inflammation in obesity." (PMID 28319103, 2017). "Whereas, IL‐18 expression in metabolic disease was investigated 10, 11, 12, modulations in the expression of IL‐18R with regard to IL‐18 and other inflammatory markers in the adipose tissue in obesity and/or T2D still remain unclear." (PMID 28508444, 2017). "Lack of Il18 but not Il18r1 in mice led to increased susceptibility to dietary obesity." (PMID 26656097, 2015). "However, in the context of severe obesity, whether IL-18 is a biomarker of comorbid conditions or a mediator of disease is unclear." (PMID 24555158, 2013). "Obesity is associated with low-grade chronic inflammation and adipose tissue is a main source of excess production of cytokines like tumour necrosis factor-α (TNF-α), interleukin-18 (IL-18), IL-1, IL-8, monocyte chemoattractant protein-1, and C reactive protein (CRP)." (PMID 23431426, 2013). "Thus, the association between the polymorphism of IL-18, a member of the IL-1 family, and obesity without metabolic disease was a primary focus of this study." (PMID 22531046, 2012). "Therefore, it has been hypothesized that the increased IL-18 concentrations have a pathophysiological role in obesity and metabolic syndromes." (PMID 22531046, 2012). "IL-18 (R2:0.355, P < .01) and IL-1ra (R2:0.287, P < .05) correlated with BMI, whereas IL-1α did not.Conclusions.Accumulating data indicate the importance of the endocrine function of adipose tissue for the pathophysiological consequences of obesity-related co-morbidities." (PMID 20169140, 2010). "In obesity, chronic stimuli like free fatty acids and oxidized lipoproteins maintain NLRP3 activation, increasing IL-1β and IL-18 levels." (PMID 40004007, 2025).
Obesity (continued). "All in all, the metabolic deterioration from obesity healthy to obesity abnormal correlated with altered levels of hs-CRP, leptin, adiponectin, chemerin, and IL-18." (PMID 39940942, 2025). "Along with elevated levels of hs-CRP, we observed a significant borderline increase in IL-18 and a six-fold increase in potentially harmful gut bacteria (CAG-Pathogen) in individuals with cardiometabolically abnormal obesity." (PMID 39940942, 2025). "Patients with obesity and T2D exhibited decreased (P < 0.05) jejunum gene expression levels of NLRP6 and its main effector IL18 together with increased (P < 0.05) mRNA levels of inflammatory markers." (PMID 38315242, 2024). "Pro-inflammatory factors such as tumor necrosis factor-α (TNF-α), interleukin 6 (IL-6), interleukin 8 (IL-8), interleukin 18 (IL-18), interleukin 1β (IL-1β), or chemokine ligand 2 (CCL2) are also produced by WAT and are all increased in obesity." (PMID 38474344, 2024). "High levels of IL‐18 in PCOS patients were found to be correlated with insulin sensitivity and obesity." (PMID 39036884, 2024). "Nowadays, evidence is apparent that obesity-induced activation of inflammatory cytokines (e.g., NLRP3, IL-1β, IL-18) is a major culprit behind the adiposity-related metabolic complication." (PMID 37935689, 2023). "In obesity, factors such as TNF-α, IL-18, IL-6, and iNOS are released by M1 ATMs, leading to reactive atrophy of skeletal muscle tissue and a decrease in the number of muscle cells." (PMID 38001499, 2023). "Here, we showed that BAT-selective depletion of IL18 or NCC reduced BAT thermogenesis and lipolysis, and increased HFD-induced obesity and metabolic syndrome." (PMID 36482059, 2022). "However, as for leptin, obesity could reflect a state of IL-18 resistance." (PMID 36313762, 2022). "Here we report a role for NCC- and IL18r-mediated IL18 activities in BAT thermogenesis and WAT insulin sensitivity that mitigates obesity and diabetes." (PMID 36482059, 2022). "Interleukin-18 (IL18) is an important proinflammatory cytokine involved in the pathogenesis of acute coronary events and type 2 diabetes mellitus, and it is associated with the modification of obesity and metabolic syndrome risk, although the underlying mechanisms remain unclear." (PMID 35207726, 2022). "In addition, more pre-clinical studies involving IL-18 regulatory steps, such as maturation by inflammasome, retention by IL-18BP or antagonism by anti-IL-18 or anti-IL-18R antibodies could open new therapeutic options for patients with metabolic diseases such as obesity, diabetes, and NAFLD/NASH." (PMID 36313762, 2022). "The present results of our analysis in the liver indicate a site-dependent NLRP3 inflammasome regulation throughout obesity, since overexpression of NLRP3, CASP1 (p20), and IL-18 (p18) took place only at 16 week of DIO." (PMID 34805147, 2021). "Nonetheless, the regulation of ovarian inflammation in late obesity (16- week HFD) seems to be independent from NLRP3 inflammasome activation, as IL-18 and CASP1 mature proteins were significantly downregulated." (PMID 34805147, 2021). "However, in pathological conditions such as obesity, dysfunctional adipocytes mostly produce and release pro-inflammatory adipokines such as leptin, tumour necrosis factor-α (TNFα), interleukin 6 (IL-6), interleukin 18 (IL-18), or resistin, which have atherogenic effects." (PMID 33081064, 2020). "We found a regulation of IL-6, IL-8, IL-15, IL-18, and FGF21 in plasma by exercise, while obesity status increased IL-13 and decreased IL-8 and SPARC in the circulation." (PMID 32132925, 2020). "Obesity-induced chronic inflammation leads to overexpression of TNFα (tumor necrosis factor alpha), IL6 (interleukin 6), IL18 (interleukin 18), and other pro-inflammatory cytokines that are also known to inhibit adiponectin." (PMID 31121868, 2019).
Obesity (continued). "In summary, it is likely that the two inflammasome sensors, NLRP1 and NLRP3, exert opposite effects in obesity; NLRP1 cleavage of IL-18 acts to limit metabolic dysfunction, while NLRP3 activation of IL-1β is detrimental and promotes glucose intolerance." (PMID 29515457, 2018). "The anti-obesity ability of NLRP1 inflammasome appears to be dependent on IL-18, as knockout of IL-18 reverses its protective effects." (PMID 30319645, 2018). "The asthma and obesity groups showed an increase in cytokine of IL-17A, IL-4, IL-6, TNF, IL-1β and IL-18 in the BALF compared with normal controls." (PMID 29160418, 2017). "Overall inflammatory activity, in addition to adipose tissue mass, provided information on a pathogenetic link between obesity and OPN and IL-18." (PMID 23675517, 2013). "A number of host factors including SNPs of interferons IL28A, IL28B, IL29, interferon-γ, MBL, IL -10, IL-18, CTLA4, TRAIL, TGF-β, MX1, Osteopontin, LMP7, OAS1 genes, insulin resistance, obesity and ethnicity, have been found to modulate the treatment response." (PMID 24079723, 2013). "In summary, the serum IL18 level was increased in PCOS patientsl, and correlaed with IR, obesity and hyperandrogenism." (PMID 21244650, 2011). "In order to investigate the possible roles of IL-18 in the pathogenesis of PCOS, we studied the serum level of IL-18 in PCOS patients, as well as it's correlation with IR, obesity and hyperandrogenism." (PMID 21244650, 2011). "IL-18 level was increased in PCOS patients, and correlated with insulin resistance, obesity and hyperandrogenism." (PMID 21244650, 2011). "Lactoferrin has been shown to ameliorate obesity-induced endothelial dysfunction and PVAT whitening by inhibiting Tak1-dependent interleukin-18 (IL-18) secretion from perivascular adipocytes, thereby relieving IL-18–mediated suppression of NO production and restoring endothelial function." (PMID 41528566, 2026). "Additionally, it has been demonstrated that NLRP1-derived IL-18 prevents obesity, suggesting that sources other than the NLRP3 inflammasome contribute substantially to IL-18 production." (PMID 39496966, 2025). "Compared to individuals with adequate weight, those with overweight/obesity but without diabetes and individuals with type-2 diabetes show increased expression of the IL-18R and IL-18 mRNA/protein." (PMID 39940942, 2025). "Likewise, in females with obesity, vaccinated mice had significantly lower levels of eotaxin, GM-CSF, GRO-α, IL-1β, IL-2, IL-5, IL-6, IL-12p70, IL-17A, IL-18, IP-10, MCP-1, MCP-3, MIP-1α, MIP-1β, MIP-2α, and TNF-α compared to unvaccinated controls." (PMID 41488663, 2025). "For instance, mice lacking IL-18 or the IL-18 receptor (IL-18R) develop obesity and insulin resistance." (PMID 39940942, 2025). "Circulating levels of the intestinal inflammatory factors CCL5 and IL-6 as well as the IL-18/IL-18BP ratio were increased (P < 0.05) in patients with obesity with and without T2D being also significantly associated with endotoxin levels." (PMID 38315242, 2024). "Obesity has a significant inflammatory component and overweight individuals have increased serum levels of inflammatory cytokines such as tumor necrosis factor alpha (TNF-α), CRP and interleukins (IL-6, IL-18)." (PMID 38330593, 2024). "Numerous studies found a relationship between IL-18 levels and obesity, but not between IL-18 and PCOS specifically." (PMID 38540173, 2024). "A possible explanation for the effects on the Sertoli cell and sperm parameters is that severe obesity may trigger the activation of the NLRP3 inflammasome complex, leading to the production of the proinflammatory cytokines, IL-1β and IL-18." (PMID 36675601, 2023). "Additionally, some of the protective effects of the NLRP3 inflammasome may also be mediated via IL-18, as deficiency of Il18 in diabetes-prone non-obese diabetic mice induces the spontaneous development of obesity, hyperglycemia and IR, which can be reversed by IL-18 administration." (PMID 37239938, 2023).
Obesity (continued). "An increase in IL-1β, IL-18, TNF-α, inflammasome NLRP3 activation, astrogliosis, and BBB permeability in the brain areas involved in the control of the intake of food such as the LH and hippocampus are the hallmarks of obesity-induced neuroinflammation." (PMID 36674982, 2023). "Various other obesity-related lipid metabolites, such as homocysteine, free fatty acids, ROS, uric acid, and cholesterol crystals, activate the NLRP3 inflammasome to induce the production of IL-1β and IL-18 by macrophages." (PMID 38001499, 2023). "On the contrary, the relative abundance of PCSK9 and NLRP3 positively correlated with obesity diagnosis indices (body weight, fat mass and Lee’s index), abnormal sperm rate, pyroptosis markers including Caspase-1, GSDMD, IL-1, IL-18 and the level of lipid metabolizing hormone (TG, TC and LDL)." (PMID 37935689, 2023). "T2DM is an obesity-related metabolic syndrome with the sustained activation of the NLRP3 inflammasome, which is a critical component of the innate immune system mediating caspase-1 activation and the secretion of proinflammatory cytokines IL-1β/IL-18." (PMID 36558167, 2022). "It was reported that mice lacking the NLRP1 inflammasome showed reduced VAT IL18 production and lipolysis, leading to obesity and metabolic syndrome." (PMID 36482059, 2022). "Indeed, the rapid upregulation of NLRP3 protein in early obesity (after 4- week HFD treatment) was followed by a consistent downregulation of NLRP3, IL-18, and CASP1 in late obesity (after 16- week HFD)." (PMID 34805147, 2021). "In patients with obesity, overproduction of cytokines evokes a preexisting chronic inflammation, since adipocytes secretion of pro-inflammatory molecules (e.g. MCP-1, IL-6, IL-18, TNF-α, IL-1β) together with a decrease of anti-inflammatory cytokines (e.g. IL-10) has been reported." (PMID 34038475, 2021). "It has been found that plasma IL-18 levels are significantly associated with HOMA-IR, and this relationship is independent of obesity and diabetes status." (PMID 32517700, 2020). "IL-18 levels were increased in PCOS patients and correlated with IR and obesity." (PMID 31906930, 2020). "As IL-18 plays a role in inflammation it is not surprisingly that circulating IL-18 levels are elevated in human obesity and in patients with type 2 diabetes." (PMID 29342149, 2018). "Moreover, IL-18 Production is regulated by the NLRP1 Inflammasome in the context of metabolic stress, Preventing Obesity and Metabolic Syndrome42." (PMID 29884798, 2018). "In conclusion, IL-18 mediates the cardiac dysfunction induced by a high-saturated fat and high-sugar diet, independent of food intake, obesity and hyperglycemia, showing a disconnect between diet-induced obesity, altered metabolism and cardiac dysfunction." (PMID 28394363, 2017). "IL-18 mediates diet-induced cardiac dysfunction, independent of food intake and obesity, thus highlighting a disconnect between the metabolic and cardiac effects of IL-18." (PMID 28394363, 2017). "While we cannot rule out spontaneous obesity at much later time points, we did not observe differences between WT and IL-18BPKO mice that were comparable to published reports on the absence of IL-18." (PMID 28900426, 2017). "Using IL-18 knockout mice, it has been demonstrated that lack of endogenous IL-18 results in obesity, insulin resistance, and hyperglycemia." (PMID 20490358, 2010). "Moreover, despite IL‐18 being correlated with the expression of lipases in adipose tissue in individuals with obesity, the expression of this cytokine did not correlate with markers related to weight loss and body fat 1 year after bariatric surgery." (PMID 41508774, 2026). "Higher induction of proinflammatory cytokines, IL-6 and IL-18, may indicate stronger early inflammatory response in non-responders than in females with obesity." (PMID 41488663, 2025).